PVALB (parvalbumin)
Diseases named in the same sentence as PVALB in open-access papers (continued):
Sharing a sentence is not in itself a finding about the gene and the disease.
epilepsy (continued). "KCNA6 mRNA and KV1.6 expression were increased in the piriform cortex parvalbumin interneurons following induction of epilepsy, demonstrating KV1.6 expression in inhibitory interneurons." (PMID 36318112, 2023). "In this study, we assessed epilepsy-induced changes in parvalbumin (PARV) immunoreactive neurons of the medial septum (MS) and of the magnocellular preoptic nucleus (MCPO) using the kainic acid (KA) model in rats." (PMID 38188006, 2023). "Based on findings that PNNs regulate the synaptic balance of structural excitatory and inhibitory synapses on parvalbumin-expressing interneurons these dense ECM-structures are interesting for epilepsy research." (PMID 37143468, 2023). "The parvalbumin (PV) subpopulation of inhibitory neurons regulates excitatory pathways in the hippocampus and extrahippocampal regions in epilepsy." (PMID 38136181, 2023). "Changes in parvalbumin expression are deeply related to epilepsy, which is considered one of the most disabling neuropathologies." (PMID 35250498, 2022). "Considering the significant role in regulating many physiological processes, such as intracellular signaling and synaptic transmission, changes in parvalbumin are deeply related to epilepsy." (PMID 35250498, 2022). "Due to the myriad of mechanisms of actions in neurotransmitters, intracellular and anti-inflammatory pathways, it is difficult to establish the direct modulation of parvalbumin function in epilepsy and its comorbidities." (PMID 35250498, 2022). "For example, studies in experimental epilepsy have shown important alterations in the GABAergic/parvalbumin circuitry of the olfactory bulb, the basolateral amygdala, and the hippocampus." (PMID 35449517, 2022). "Reduced numbers of parvalbumin cells, altered morphology, immature electrophysiological properties with lower firing rates, and power of gamma oscillations play a role in Epilepsy and its comorbidities." (PMID 35250498, 2022). "In epilepsy basic research, optogenetic manipulation provided new insights into the role of parvalbumin in seizure onset and spread." (PMID 35250498, 2022). "A potential role of RS as hub between subcortical and cortical regions in epilepsy was supported by increased numbers of parvalbumin-positive (PV+) interneurons together with enhanced inhibitory synaptic activity and neuronal excitability in pyramidal neurons." (PMID 34296168, 2021). "Another study investigated the disrupted balance between inhibition, such as parvalbumin-positive GABAergic interneurons, and excitation within the neuronal networks for acupuncture and epilepsy." (PMID 35096291, 2021). "Loss of GABAergic interneurons, especially those containing parvalbumin (PARV), has been documented in human epilepsy and in several different experimental models of the disease, suggesting that it is critically involved in epileptogenesis." (PMID 33391173, 2020). "The parvalbumin subpopulation seems to bemarkedly affected in epilepsy and ASDs, possibly because these cells areless proficient at inhibiting pyramidal cells." (PMID 29086765, 2018). "Parvalbumin-immunoreactivity was shown to disappear from surviving inhibitory interneurons in an animal model of epilepsy." (PMID 28116310, 2017). "Together, these changes suggest that PB impacts inhibitory neurotransmission, and raise the possibility that these changes could in turn, impact PB efficacy–reduced parvalbumin neurons, for example, would be expected to worsen epilepsy outcomes." (PMID 38606173, 2024). "Previous studies showed that deletion of Ank3-1b, a BD-associated variant of Ank3 in mice leads to increased firing threshold and diminished action potential dynamic range of parvalbumin (PV) interneurons and absence epilepsy, thus providing a biological mechanism linking epilepsy and BD." (PMID 38123552, 2023). "Therefore, advances in potential therapeutic interventions will be discussed, as we will present key findings on the parvalbumin role on epilepsy and epilepsy comorbidities." (PMID 35250498, 2022).
epilepsy (continued). "Finally, since parvalbumin is involved in many higher cognitive processes, its altered function is related to other psychopathologies and psychiatric comorbidities in Epilepsy." (PMID 35250498, 2022). "Considering this, chemogenetic and optogenetics approaches could provide essential insights into parvalbumin’s role in Epilepsy and psychiatric comorbidities." (PMID 35250498, 2022). "Using a unique feature of certain in vitro epilepsy models, we show that without this glutamatergic feedback, intense activation of interneurons causes parvalbumin and glutamate decarboxylase 1 mRNA expression to increase." (PMID 30110232, 2018). "Moreover, it has been reported that TrkB signaling in parvalbumin-positive interneurons is important for gamma-band network synchronization which is affected in epilepsy." (PMID 23840662, 2013). "Similarly, TMS pulses interfere with GABAergic functioning and possibly the parvalbumin fast-spiking interneurons changing synchronization and cortical excitation that may present abnormally in patients with epilepsies and/or psychiatric disorders." (PMID 35250498, 2022). "It is likely that novel treatments targeting mitochondria to prevent the dysfunction of these highly important organelles and to preserve the functioning of parvalbumin+ interneurons may benefit an array of patients with common epilepsies and neurodevelopmental disorders." (PMID 35790454, 2022). "Interestingly, parvalbumin interneurons undergo neurodegeneration in SE models of epilepsy." (PMID 26020770, 2015). "At this point, we cannot entirely rule out that a reduced expression of parvalbumin and somatostatin takes place in cellular subcompartments of interneurons within the GGs without loss of the cells themselves − similar to what has been suggested in epilepsy-associated hippocampal sclerosis." (PMID 36538906, 2022). "The comprehension of parvalbumin mechanisms in epilepsies provides essential insights into new treatments and non-invasive approaches, such as transcranial magnetic stimulation (TMS)." (PMID 35250498, 2022). "This suggests that the absence of parvalbumin may be involved in the development of epilepsy and psychosis." (PMID 39858450, 2025). "Similarly, in a study of epilepsy, hM3Dq was used to transfer PV-INs into the hippocampal epileptic foci, and CNO activation increased the firing rate of parvalbumin neurons and inhibited the firing rate of glutamatergic neurons, thereby alleviating epileptic seizures." (PMID 40691203, 2025). "Besides these valuable recent discoveries, the role of parvalbumin in epilepsy has not yet been unraveled." (PMID 35250498, 2022). "Additionally, since parvalbumin basket cells and molecular layer interneurons express GABAAR δ subunits, it is possible that changes in interneuronal tonic GABA currents could influence their excitability and alter GC sIPSC frequency as observed in epilepsy." (PMID 35360164, 2022).
Anxiety (48 papers, 2013 to 2026). Intense feelings of nervousness, tension, or panic often arise in response to interpersonal stresses. "For example, adolescent stressed rats show increased anxiety-like behaviours, decreased sociability, cognitive deficits, and increased responsivity to psychostimulants, along with hippocampal hyperactivity, parvalbumin neuron loss, and an overactive dopamine system." (PMID 36572669, 2022). "Within the BLA, parvalbumin cells (PV+) are the largest population of GABAergic inhibitory interneurons, directly influencing output of primary excitatory neurons, and these cells have been directly implicated in anxiety-like behavior." (PMID 34512237, 2021). "This study uses a mouse model of stress-induced anxiety-like and depressive-like behaviors to show a novel mechanism, adaptation of prefrontal parvalbumin (PV) neurons, that may underlie the greater susceptibility of females to stress-related psychopathologies." (PMID 36808099, 2023). "Because the dorsomedial striatum is more heavily involved in associative and emotional processing, anxiety‐like behavior could have been spared from chronic nicotine if the activity of fast‐spiking parvalbumin interneurons in the dorsomedial striatum were intact." (PMID 32767546, 2021). "There is considerable evidence implicating the basolateral amygdala (BLA) in the network communication of anxiety and fear, a process demonstrated to involve parvalbumin-positive (PV) interneurons." (PMID 39746805, 2025). "This study aims to explore the neural mechanisms by which stress-induced imbalances in the basolateral amygdala (BLA) parvalbumin interneurons (PV-INs) and glutamatergic neurons lead to anxiety." (PMID 40691203, 2025). "Chemogenetic studies extend this causal link: silencing parvalbumin- or CCK-positive interneurons in the basolateral amygdala precipitates depressive- and anxiety-like behaviours, whereas their activation rescues mood, underscoring circuit specificity." (PMID 41373485, 2025). "The homozygous Bronx waltzer (bv) mouse, which shows hearing impairment, also exhibits anxiety accompanied by a reduction in cortical parvalbumin (PV)-positive GABAergic interneurons." (PMID 38229888, 2024). "Accordingly, early life stressors such as parental separation and social isolation were shown to lead to parvalbumin abnormalities in hippocampus and prefrontal cortex, and along with increased PNNs these changes can exacerbate anxiety and hyperactivity." (PMID 39739746, 2024). "More typically, long-term fluoxetine treatment normalizes hippocampal parvalbumin-positive interneurons number and glucocorticoid signaling of Angelman syndrome model mice, which is important for the restoration of anxiety-like behaviors." (PMID 38716113, 2024). "Female parvalbumin neurons adapt after shorter periods of chronic stress than male neurons, paralleling earlier emergence of anxiety-like behaviors in females." (PMID 36808099, 2023). "EA effectively mitigates both CIP and anxiety by activating parvalbumin neurons in the anterior cingulate cortex, inducing an increase in neurotensin/neurotensin receptor expression, and inhibiting protein kinase Mzeta activity." (PMID 37948105, 2023). "Studies indicate that the inhibition of a subpopulation of hippocampal parvalbumin-expressing interneurons induced a long lasting anxiety- or fear-like behavior." (PMID 37077956, 2023). "It is important to note, though, that the implication of parvalbumin in anxiety-like behaviour seems to be highly region- and sex-specific: as such, there is also evidence for an anxiogenic effect of PV+ cell activation." (PMID 35907861, 2022). "Cell type-specific deletion of Fmr1 in parvalbumin-expressing neurons resulted in anxiety-like behavior, impaired social behavior, and dysregulated de novo protein synthesis." (PMID 35768828, 2022).
Anxiety (continued). "In animal models, adult male rats exposed to chronic social isolation show depressive- and anxiety-like behaviors and reduce the numbers of parvalbumin-positive interneurons in the dorsal hippocampus." (PMID 35879288, 2022). "Mice with deletion of CTCF in parvalbumin-expressing neurons induced a decrease in anxiety-like behavior and a social impairment at early age, followed by gradual deficits in motor function." (PMID 35379308, 2022). "In this study, we established a chronic inflammatory pain model and observed that this model induced anxiety-like behaviors and decreased the numbers of parvalbumin (PV) and somatostatin (SOM) positive cells." (PMID 34290586, 2021). "Another is MIAT (also known as GONAFU); RNA levels were found to be expressed at higher levels in parvalbumin GABAergic interneurons in SZ subjects and have been found to regulate fear-related anxiety traits in mice." (PMID 28321286, 2017). "The results suggest that rearing in the enriched environment augmented parvalbumin-positive specific neurons in the basolateral amygdala, which induced behavioral plasticity that was reflected by a decrease in anxiety-like behavior in anxiogenic situations." (PMID 23347699, 2013). "The present findings suggest that the expression levels of DLX5/6 and DLX6-AS1, regulating differentiation and function of Parvalbumin-positive neurons in the adult brain, also affects anxiety and depression and pave the way for further analyses on the mechanism of action of antidepressants." (PMID 39120293, 2024). "Within the hippocampus, these mice demonstrate susceptibility to glucocorticoid exposure, disrupted glucocorticoid receptor signaling, and reduced number of parvalbumin-positive inhibitory interneurons, resulting in chronic stress, hippocampal hyperactivity and ultimately increased anxiety." (PMID 38716113, 2024). "Improvements in anxiety and spatial learning were evident, which coexisted with the normalisation of parvalbumin interneurons early in development, and long-term organisation of cortical myelinated fibres as well as absence of the inflammation-induced increase in MD." (PMID 36309753, 2022). "Importantly, the modulation of BLA network/oscillatory states via parvalbumin (PV)-positive GABAergic interneurons has been shown to control the behavioral expression of fear and anxiety." (PMID 35788104, 2022). "Parvalbumin–/– mice are also more related to social behavior deficits, anxiety-like, and cognitive impairment, suggesting that these deficits could be related to autism spectrum symptoms." (PMID 35250498, 2022). "We used a battery of behavioral tests to evaluate anxiety, working memory, and sensory processing, and immunohistochemistry to quantify changes in parvalbumin-expressing inhibitory interneurons (PV+ INs), perineuronal nets (PNNs), as well as microglia density and morphology." (PMID 35002614, 2021). "We hypothesized that the sleep fragmentation effects on anxiety are dependent on its duration and mediated by increased oxidative stress and alterations in the number of parvalbumin (PV+) interneurons in the hippocampus." (PMID 34471462, 2021). "We hypothesized that alterations of localized brain areas and cholecystokinin (CCK) and parvalbumin (PV) expression could induce anxiety-like behavior in type 2 diabetic Otsuka Long-Evans Tokushima fatty (OLETF) rats." (PMID 32938363, 2020). "Furthermore, as reported in previous studies, peripubertal administration of diazepam decreased the hyperdopaminergic state and the heightened anxiety levels in MAM rats, which is probably contributed by the attenuated loss of parvalbumin interneurons." (PMID 27432008, 2016). "Here we investigated whether rearing in enriched environment could modify the expression of parvalbumin-positive neurons in the basolateral amygdala and anxiety-like behavior." (PMID 23347699, 2013).
Anxiety (continued). "Novel findings have also highlighted that CUS increases parvalbumin (PV) expression and the number of PV+ neurons (fast-spiking GABAergic neurons that are powerful regulators of local network activities), particularly in female mice, along with heightened anxiety-like behaviors." (PMID 39519293, 2024). "However, we found reduced expression of parvalbumin in medial prefrontal cortex, which could be rescued in part by adult overexpression of Otx2 specifically in choroid plexus, resulting in increased anxiety-like behavior." (PMID 33963285, 2021). "Increased parvalbumin expression and deregulated AMPK have been considered important in mediating anxiety/depression-like behaviors related to CUS exposure." (PMID 39519293, 2024). "Specifically, female rats with anxiety-like behavior had increased BDNF concentration in the HIP and cortex and decreased neuropeptide Y as well as parvalbumin interneurons in the CA1 region." (PMID 36159923, 2022). "High prenatal androgen excess may lead to dysregulation of neuropeptide Y, parvalbumin, and BDNF, leading to increased anxiety-like behavior." (PMID 36159923, 2022). "Furthermore, recent studies demonstrated that suppressing parvalbumin neuron activity in the BLA upregulates anxiety-related behaviors similar to the increases in anxiety seen following GPR83 knockdown in the BLA." (PMID 34512237, 2021). "Recently, our work demonstrated that exposure to chronic mild stress increases prefrontal PV mRNA expression and the number of parvalbumin (PV+)-expressing interneurons, which corresponds with heightened anxiety-like behaviors in female, but not male, mice." (PMID 31875035, 2019). "Activation of SC parvalbumin-positive (PV+) neurons, which receive direct visual input from retinal ganglion cells (RGCs) and selectively respond to looming threats, increases heart rate, and CGRPPBN neurons contribute to tachycardia and anxiety-like behaviors." (PMID 40344067, 2025).